CCDST (cervical cancer associated DHX9 suppressive transcript)
Synonyms: AL589986.2; lnc-CCDST; FLG-AS1; LINC02962
Gene: Long non-coding RNA gene on chromosome 1 (152,165,553 to 152,445,456, forward strand). Ensembl gene ENSG00000236427.
Diseases named in the same sentence as CCDST in open-access papers:
CCDST is named in the same sentence as 3 diseases in open-access papers, as found by Europe PMC text mining. Sharing a sentence is not in itself a finding about the gene and the disease. The quoted sentences say what the papers report.
cervical cancer (6 papers, 2020 to 2025). A primary or metastatic malignant neoplasm involving the cervix. "In cervical cancer (CC) cells, lnc-CCDST is downregulated via the human papillomavirus-encoded E6 and E7 oncoproteins, allowing DHX9 to accumulate and result in enhanced invasion and angiogenesis." (PMID 33437516, 2020). "However, in human papillomavirus (HPV)-infected cervical cancer, the virus-encoded proteins lead to a decrease of CCDST expression and consequently, to the increase of DHX9 abundance to induce malignant behaviors." (PMID 32992718, 2020). "LINC02962, also known as lnc-CCDST, was found to be significantly downregulated in cervical cancer tissues and bind to pre-carcinogenic DHX9 and E3 ubiquitin ligase MDM2, thereby affecting cervical cancer cell invasion and angiogenesis." (PMID 37928532, 2023). "High-risk human papillomavirus (HPV) impairs the interaction between MDM2 and DHX9 and the degradation of DHX9 by inhibiting the expression of lnc-CCDST, thereby promoting the movement and angiogenesis of cervical cancer." (PMID 36338707, 2022). "Lnc-cervical cancer DHX9 suppressive transcript (lnc-CCDST) binds DHX9, acts as a scaffold to enhance MDM2-DHX9 binding and thus induces DHX9 degradation." (PMID 33437516, 2020). "In cervical cancer cells, the proto-oncogene DHX9 binds to the lncRNA lnc-CCDST and MDM2 to regulate cell invasion and angiogenesis." (PMID 35410446, 2022).
CCDST also shares sentences with these, for which no sentence is quoted: cancer (1 paper); tumor (1).